CXCR2 (C-X-C motif chemokine receptor 2)
Diseases named in the same sentence as CXCR2 in open-access papers (continued):
Sharing a sentence is not in itself a finding about the gene and the disease.
ovarian tumor (7 papers, 2010 to 2023). "CXCR2 is overexpressed in ovarian tumors; its overexpression is associated with poor survival for patients with ovarian cancer." (PMID 26414070, 2015). "We went on to demonstrate that T-cells which co-express A20-28z and CXCR2 achieve enhanced tumor control in advanced pancreatic and ovarian tumor xenograft models." (PMID 31091832, 2019). "In summary, our findings reveal the CXCR2-mediated chemokine axis as potential pathways conferring tumor progression from continued treatment with sorafenib in ovarian tumors." (PMID 26414070, 2015). "CXCL8-CXCR1/CXCR2 signaling pathways might form complex crosstalk among different cell types within the ovarian tumor microenvironment, thereby modulating the behaviors of different cells." (PMID 37765018, 2023). "Therefore, CXCL8-CXCR1/CXCR2 signaling pathways through autocrine and paracrine mechanisms form complex crosstalk among the cells in the ovarian tumor microenvironment." (PMID 37765018, 2023). "Therefore, understanding CXCL8-CXCR1/CXCR2 signaling pathways in the ovarian tumor microenvironment could provide theoretical support for targeted therapies." (PMID 37765018, 2023). "As ovarian tumor cells undergo the EMT, those cells activate WNT signaling to promote IL-8 expression and further reinforce an IL-8/CXCR2/WNT feedback loop." (PMID 34799554, 2021).
renal carcinoma (7 papers, 2018 to 2025). A carcinoma arising from the epithelium of the renal parenchyma or the renal pelvis. "Nevertheless, CXCR2-driven effects remain central, as CXCR2-knockout mouse models of prostate and renal cancers exhibit comparable tumor suppression." (PMID 41155662, 2025). "CXCR2 knockout (KO) mice had a significantly reduced tumor burden in other cancers, such as murine lung, prostate, and renal cancer models, compared to CXCR2 wild-type (WT) mice." (PMID 34638514, 2021). "Furthermore, chemokines such as CXCR2 also improved the trafficking and infiltration of NK cells into the tumor microenvironment of renal cancer, thus providing great insight into genetically engineering CXCR2 on CAR-NK cells." (PMID 38726000, 2024). "Recent data has shown that TNF-α significantly increased the expression of CXCR2 and CXCR3 and their related ligands in renal cancer cells enhancing the migration, invasion and EMT." (PMID 29416784, 2018).
acute respiratory distress syndrome (6 papers, 2019 to 2024). Progressive and life-threatening pulmonary distress in the absence of an underlying pulmonary condition, usually following major trauma or surgery. "Indeed, CXCR2 activity correlates with neutrophils hyperactivity and with outcomes such as acute respiratory distress syndrome (ARDS) whereas reduced CXCR2 function seen in inflammatory environments may impair neutrophil functions." (PMID 31552051, 2019).
bone cancer (6 papers, 2014 to 2025). A primary or metastatic malignant neoplasm affecting the bone or articular cartilage. "This study suggests that CXCL5 and CXCR2 inhibitors are attractive therapeutic targets that may have efficacy in treating or inhibiting the formation of metastatic bone tumors that are dependent on the CXCL5/CXCR2 signaling axis and resistant to current therapies." (PMID 31562303, 2019). "Research in a rat model of bone cancer pain revealed that liquiritin mitigates pain by impeding the spinal cord astrocyte CXCL1 and neuronal CXCR2 pathways." (PMID 39295943, 2024).
colorectal tumors (6 papers, 2015 to 2025). "In colorectal tumors, CXCR2 was identified on tumor cells, endothelial cells, infiltrating neutrophils, and macrophages, and CXCR2 overexpression was identified in CRC liver metastases." (PMID 26320187, 2015). "CXCL1 is highly expressed in human colorectal tumors, and both CXCL1 and CXCL2 are involved in IBD and believed to promote tumor angiogenesis by directly activating their shared receptor, CXCR2, on endothelial cells." (PMID 29720595, 2018). "Therefore, a unique cohort of synchronously resected primary colorectal tumours and matched liver metastases (cohort 2) was stained for the main cognate receptor of CXCL8, CXCR2, by IHC." (PMID 35879507, 2022).
heart failure (6 papers, 2014 to 2025). Inability of the heart to pump blood at an adequate rate to meet tissue metabolic requirements. "By studying and exploring the role and mechanism of the CXCR2 inhibitor Nav in MI-induced heart failure, we provide an experimental basis for CXCR2 inhibitors becoming a new therapeutic target for MI in the future." (PMID 40183084, 2025). "In addition, we can also find reports about the increased levels of IL-8, CXCR1 and CXCR2 in CAD patients, which is supposed to be involved in the pathogenic mechanisms in heart failure." (PMID 25514790, 2014).
liver diseases (6 papers, 2016 to 2024). "CXCL1 exerts its function in liver disease mainly by regulating neutrophils, Kupffer cells and myeloid-derived suppressor cells (MDSCs), and its specific receptor CXCR2 is highly enriched." (PMID 37037815, 2023). "At pharmacological level, CXCR2-directed therapies are already under investigation for the treatment of cardio-metabolic and liver diseases." (PMID 38327649, 2023).
myocardial infarction (6 papers, 2012 to 2025). Gross necrosis of the myocardium, as a result of interruption of the blood supply to the area, as in coronary thrombosis. "This study provides new insights for the use of CXCR2 inhibitors as new therapeutic options for myocardial infarction in the future." (PMID 40183084, 2025). "Our data show circulating exosomal mRNA CXCR2 to be a potential biomarker for AMI with high diagnostic efficiency and constituted a resource for further investigation of the functional implications of neutrophils in myocardial infarction." (PMID 34490374, 2021). "Similarly, expression of the chemokine receptor CXCR2, deficiency of which limits neutrophil recruitment and the extent of myocardial infarction size, was not altered by RIC in the presence or absence of brachial plexus block." (PMID 34589791, 2021). "Furthermore, CXCR2 may play a crucial cardio-protective role in myocardial infarction through enhanced myeloid progenitor production and upregulation of cardiac adhesion molecules." (PMID 34490374, 2021). "Thus, CXCR2 may play a key role in leucocyte recruitment during the inflammation and pathogenesis of myocardial infarction." (PMID 25267411, 2014).
thyroid cancer (6 papers, 2014 to 2025). "The main findings of the present study are represented by the impact on the CXCR2 mRNA and protein-membrane expression modulation and for the thyroid cancer cell migration after treatment with AZD5069." (PMID 38900374, 2025). "Our evaluation showed that the CXCR2 signalling pathway is a key driver of thyroid cancer cell motility and is a critical chemokine receptor targeted by AZD5069 via selective CXCR2 antagonism." (PMID 38900374, 2025). "According to transcriptome sequencing, antitumor chemokine regulatory genes (CXCR3) were upregulated, and protumor chemokine regulatory genes (CCR3, CXCL1, CXCL2, CXCL3, CXCL8, and CXCR2) were downregulated after MWA in thyroid cancer." (PMID 38779358, 2024). "This study aimed to evaluate if the targeting of CXCR2 by its selective antagonist, AZD5069, could modulate CXCL8-mediated pro-tumorigenic effects in thyroid-cancer (TC) cells in vitro." (PMID 38900374, 2025). "It was hypothesized that CXCL8 would exert its active role in thyroid cancer progression by paracrine binding to CXCR1 and CXCR2 expressed on the surface of PTC cells." (PMID 29977225, 2018).
atrial fibrillation (5 papers, 2020 to 2022). A disorder characterized by an electrocardiographic finding of a supraventricular arrhythmia characterized by the replacement of consistent P waves by rapid oscillations or fibrillatory waves that vary in size, shape and timing and are accompanied by an irregular ventricular response. "In silico analysis has shown some association of CXCR2 with atrial fibrillation—potential miRNAs that decrease CXCR2 expression are miR-5001-3p and miR-4283." (PMID 35216283, 2022). "This suggests that if CXCR2 has a role in the pathogenesis of atrial fibrillation, then it is activated by a ligand other than CXCL1." (PMID 36613652, 2022). "Therefore, the diagnostic efficacy of CYBB, CXCR2, and S100A4 in different populations and its role in the occurrence of atrial fibrillation still need more external validation." (PMID 35305619, 2022). "At the same time, atrial fibrillation patients have lower CXCL1 expression in the atrium heart tissue and higher CXCR2 expression compared to healthy subjects." (PMID 36613652, 2022). "Patients with atrial fibrillation have higher levels of CXCL1 and CXCR2+ monocytes in their blood." (PMID 36613652, 2022). "In humans, an important role in atrial fibrillation may be played by CXCL7/pro-platelet basic protein (PPBP), a ligand of CXCR2." (PMID 36613652, 2022).
Cirrhosis (5 papers, 2011 to 2022). A chronic disorder of the liver in which liver tissue becomes scarred and is partially replaced by regenerative nodules and fibrotic tissue resulting in loss of liver function. "In contrast, monocytic CXCR2 expression was moderately down-regulated in patients compared to healthy controls, independent of the presence of cirrhosis." (PMID 21731723, 2011).
coronary artery disease (5 papers, 2017 to 2025). "Therefore, the aim of this study is to investigate the effects of AZD5069, a cysteine-X-cysteine chemokine receptor 2 (CXCR2) inhibitor, on coronary flow reserve and coronary structure and function in patients with coronary artery disease." (PMID 29020983, 2017). "This will help to improve understanding of the cardiovascular effects of CXCR2 inhibition in patients with coronary artery disease (CAD)." (PMID 29020983, 2017). "Therefore, in the CXCR2 Inhibition – a novel approach to treating CoronAry heart DiseAse (CICADA) study, we aim to perform a randomised, placebo-controlled, double-blind trial to investigate the effect of the CXCR2 inhibitor AZD5069 on CFR and coronary plaque morphology." (PMID 29020983, 2017).
endothelial dysfunction (5 papers, 2016 to 2025). In vascular diseases, endothelial dysfunction is a systemic pathological state of the endothelium (the inner lining of blood vessels) and can be broadly defined as an imbalance between vasodilating and vasoconstricting substances produced by (or acting on) the endothelium. "The critical roles of CCR2 and CXCR2 in further disruptions, such as endothelial dysfunction, smooth muscle cell proliferation, angiogenesis, and WBC infiltration/activation/adhesion highlight the importance of these receptors in vascular atherosclerosis." (PMID 40495291, 2025). "Accordingly, future investigations are needed to further elucidate the paracrine role of PGP in other cardiovascular disorders, as well as the relative roles of endothelial CXCR1 and CXCR2 in promoting cytokine-dependent endothelial dysfunction." (PMID 28790330, 2017). "This complex inflammatory stimulus triggers early signs of endothelial dysfunction in HAOEC (i.e., upregulation of CXCL8, CXCR2, and MMP9 genes in the presence of variable MMP9 protein activity) but extracellular matrix/angiogenesis-related changes in HAOSMC." (PMID 41227357, 2025).
ischemic stroke (5 papers, 2013 to 2023). A stroke disorder caused by obstruction of blood flow to the brain, due to thrombotic (local blood clot formation) or embolic (due to a blood clot or other material traveling from another site) event. "Also, many genes encoding chemokines, cytokines and chemokine receptors, which are involved in neuroinflammatory processes in ischemic stroke, were regulated, including Cxcr2 in endothelial cells, Ccl5, Il11 and Il6 in pericytes, Lcn2 in astrocytes and pericytes, and Il1rn in microglia." (PMID 35752654, 2022). "Expression of ligands for CXCR2 during ischemic stroke may also depend on miRNAs." (PMID 35457023, 2022). "A recent paper reports CXCL5 (that binds with CXCR1 and CXCR2 and activates the p38 MAP kinase signaling pathways) to be upregulated in ischemic stroke." (PMID 36982232, 2023). "Unfortunately, therapy of ischemic stroke with CXCL2 receptor-CXCR2 antagonists SB225002 was not successful." (PMID 24324296, 2013).
lymphoma (5 papers, 2019 to 2025). A malignant (clonal) proliferation of B- lymphocytes or T- lymphocytes which involves the lymph nodes, bone marrow and/or extranodal sites. "In the reactive tonsils (n = 4), all of the GC-Bs possessed a weaker CXCR2 protein expression compared with the lymphoma cells." (PMID 35887224, 2022). "A putative anti-tumor role of ILC2s has been proposed in a subcutaneous lymphoma mouse model, where sustained production of IL-33 induced the upregulation of CXCR2 on EL4 thymoma cells, the expansion of ILC2s and the concomitant production of CXCR2 ligands (CXCLs)." (PMID 31849977, 2019). "Owing to the highest CXCR2 mRNA expression in the de novo DLBCL and tFL lymphoma subtypes compared with GC-B, an immunohistochemical analysis of this chemokine receptor was performed." (PMID 35887224, 2022). "In a murine lymphoma model, ILC2s were able to produce a large amount of the CXCR2 ligands CXCL1 and CXCL2, and interaction with a CXCR2-expressing tumor was shown to induce massive tumor-specific apoptosis in a CXCR2-specific way." (PMID 39858045, 2025). "The chemokine receptor expression profiles of de novo DLBCL and tFL substantially differed from those of GC-B, with at least 5-fold higher expression of 15 out of the 18 investigated chemokine receptors (CCR1–CCR9, CXCR1, CXCR2, CXCR6, CXCR7, CX3CR1 and XCR1) in these lymphoma subtypes." (PMID 35887224, 2022). "Recognizing the interaction of B cell clonogenic vp17s with PAR-1, CXCR1, and CXCR2 as key events in sustaining lymphoma growth and dissemination prompts us to study whether the AT20-KLH therapeutic vaccine may represent a promising strategy for fighting AIDS-related lymphomas." (PMID 39066211, 2024).
acute lung injury (4 papers, 2016 to 2024). A condition of lung damage that is characterized by bilateral pulmonary infiltrates (pulmonary edema) rich in neutrophils, and in the absence of clinical heart failure. "Reparixin is an allosteric inhibitor of CXCR1 and CXCR2 that has been shown to inhibit neutrophil trafficking during ischemia-reperfusion injury and acid-induced acute lung injury." (PMID 38352492, 2024). "The CXCR2 antagonist SB225002 has also been reported to reduce neutrophil recruitment and pro-inflammatory factor expression in LPS-induced acute lung injury." (PMID 32706336, 2020). "Recent studies showed that CXCR2 (the receptor of CXCL1 and CXCL2) blockade results in impaired neutrophil recruitment in lipopolysaccharide-induced acute lung injury." (PMID 27447715, 2016).
AIDS (4 papers, 2016 to 2025). A syndrome resulting from the acquired deficiency of cellular immunity caused by the human immunodeficiency virus (HIV). "p17 matrix protein released by HIV+ cells interacts with leukocytes heparan sulfate proteoglycans (HSPGs), CXCR1 and CXCR2 exerting different cytokine-like activities that contribute to AIDS pathogenesis." (PMID 31673058, 2019). "This difference may be related to the unique immune microenvironment of HIV infection, and IL-8 may recruit activated lymphocytes through CXCR1/CXCR2 signaling in advanced AIDS patients." (PMID 41425969, 2025). "Further, by activating the CXCR2 and AKT signaling, HIV-1 matrix protein p17 promotes endothelial dysfunction and angiogenesis in AIDS-related vascular diseases." (PMID 27058419, 2016).
airway hyperresponsiveness (4 papers, 2011 to 2025). "CXCR2 is required for RV induction of neutrophilic airway inflammation and development of airway hyperresponsiveness as recently demonstrated in a mouse model." (PMID 24673807, 2014). "To address the contribution of neutrophils to virus-induced airway hyperresponsiveness as proposed by others, we used CXCR2 blocking Ab and CXCR2 antagonist SB225002." (PMID 21383977, 2011). "CXCR2 is also expressed on airway smooth muscle cells and in this work we showed that CXCR2 may be a key feature in the development of airway hyperresponsiveness and, Ladarixin may be acting on CXCR2 expressed on ASM cells to improve the airways hyperresponsiveness." (PMID 33123138, 2020).
appendicitis (4 papers, 2016 to 2025). Acute inflammation of the vermiform appendix. "In appendicitis patients, there was marked increases in RNAs coding for IL8 receptor-ß (IL8RB/CXCR2), and secondary granule proteins such as alkaline phosphatase (ALPL)." (PMID 41385588, 2025). "Appendicitis patients had lower level of neutrophil defensin mRNA (DEFA1,3), but higher levels of alkaline phosphatase (ALPL) and interleukin-8 receptor-ß (CXCR2/IL8RB), which was confirmed in a larger cohort of 60 patients using droplet digital PCR (ddPCR)." (PMID 27417541, 2016). "In appendicitis, where the infection can take the form of a ‘biofilm’ that is not directly accessible to the immune cells, there was marked increases in mRNAs coding for IL8 receptor-ß (IL8RB/CXCR2), and secondary granule proteins such as alkaline phosphatase (ALPL)." (PMID 35081105, 2022).
autoimmune disease (4 papers, 2015 to 2024). A disorder resulting from loss of function or tissue destruction of an organ or multiple organs, arising from humoral or cellular immune responses of the individual to their own tissue constituents. "MIF is known to be involved in the progression of inflammatory and autoimmune diseases and interacts with various receptors, including CXCR2, CXCR4, and CD74 (Bucala 2013, Morrison and Kleemann 2015)." (PMID 37740953, 2023). "As a proinflammatory mediator secreted by numerous immune cells, MIF promotes inflammation and autoimmune diseases mainly by binding with the receptor CD74 and co-receptor CD44, CXCR4, or CXCR2." (PMID 36046240, 2022).
brain injury (4 papers, 2018 to 2025). Acute and chronic (see also brain INJURIES, CHRONIC) injuries to the brain, including the cerebral hemispheres, CEREBELLUM, and brain STEM. "The expression of this miRNA is decreased in these cells in patients with ischemic stroke, and leads to increased expression of CXCR2 on granulocytes and NK cells, triggering the migration of these cells to the brain where they cause ischemic brain injury." (PMID 35216283, 2022). "In brain trauma, neuronal CXCR2 downregulation is suggested to render neurons more vulnerable to injury." (PMID 30158469, 2018). "Studies utilizing Cxcr2+/+ mice have demonstrated that CXCR2+ neutrophils significantly influence cuprizone-induced demyelination, with implications for axonal myelination and long-term recovery following traumatic brain injury." (PMID 40854886, 2025). "Moreover, the CXCR2 promoter can undergo histone acetylation on histone 3 at Lys9 (H3K9), which increases the expression of CXCR2 in the spinal cord—a process crucial for the development of chronic pain after traumatic brain injury." (PMID 35216283, 2022).